CASP1 (caspase 1)
Diseases named in the same sentence as CASP1 in open-access papers (continued):
Sharing a sentence is not in itself a finding about the gene and the disease.
multiple myeloma (9 papers, 2020 to 2025). "Myeloma cell death was associated with dual PI and Annexin-V positivity and increased expression of apoptotic genes, including CASP1, CASP8, CASP9, BAX, BID, and FASL." (PMID 36992311, 2023). "GSK591, an inhibitor of protein arginine methyltransferase 5 (PRMT5), lowers H4R3me2s levels at the caspase-1 promoter, thereby elevating caspase-1 expression and inducing pyroptosis in multiple myeloma cells." (PMID 40555741, 2025). "We have previously shown that TAMs from multiple myeloma (MM) patients exhibit an overactive inflammasome-caspase-1-axis, which drives the progression of the disease." (PMID 40759978, 2025). "This clindamycin-mediated inhibition of caspase-1 was also observable in TAMs derived from the bone marrow of multiple myeloma patients." (PMID 40759978, 2025). "Inhibition of CASP1, either by a small molecule inhibitor or by siRNA, diminished the effect of D089 in myeloma cells." (PMID 33066043, 2020). "It has been reported that PRMT5 regulates pyroptosis via inhibiting the CASP1 in myeloma cells." (PMID 37600810, 2023). "Consistent with CASP1 activation and the ballooning phenotype, a signaling cascade of HMGB1 translocation from the nucleus to the cytoplasm was observed in D089 treated myeloma cells." (PMID 33066043, 2020).
myocardial ischemia (9 papers, 2015 to 2024). A disorder of cardiac function caused by insufficient blood flow to the muscle tissue of the heart. "By contrast, calpain silencing would attenuate mice myocardial ischemia/reperfusion injury via down regulating the NLRP3/Caspase 1 axis." (PMID 35155498, 2022). "Once myocardial ischemia occurs, inflammatory factors (IL-1, caspase-1) immediately trigger the strong infiltration of neutrophils, and lymphocytes and macrophages are also involved in, that is, the inflammation phase." (PMID 34531742, 2021). "Compared with sham group, mice exposed to 45 min myocardial ischemia followed by 60, 120 or 180 min reperfusion showed significantly higher pro-caspase-1, cleaved caspase-1, pro-caspase-11 and cleaved caspase-11 protein expression in the heart, and the expression increased with reperfusion time." (PMID 34845193, 2021). "In this study, we hypothesized that DG improves acute myocardial ischemia-reperfusion injury by inhibiting neutrophil infiltration and caspase-1 activity." (PMID 29674944, 2018).
nasopharyngeal carcinoma (9 papers, 2022 to 2025). A carcinoma arising from the nasopharyngeal epithelium. "For instance, caspase-1/GSDMD mediated pyroptosis is connected with Taxol resistance in nasopharyngeal carcinoma." (PMID 37156816, 2023). "For example, the caspase-1/GSDMD-mediated pyroptosis pathway plays a crucial role in Taxol resistance in nasopharyngeal carcinoma." (PMID 37156816, 2023). "Tan IIA targets miR-125b/gasdermin D (GSDMD) and miR-145/caspase 1, which induces apoptosis of nasopharyngeal carcinoma (NPC) cells (HK1 cells) and cervical carcinoma cells (HeLa cells), respectively." (PMID 36172186, 2022). "Another study examined the role of three proteins, Nod-like receptor protein 3 (NLRP3), cysteine-aspartic acid protease 1 (Caspase-1), and Gasdermin D (GSDMD), in nasopharyngeal carcinoma (NPC)." (PMID 39744516, 2025). "In a study focusing on nasopharyngeal carcinoma (NPC), it was discovered that caspase-1 inhibition and GSDMD knockout could induce a Taxol-resistant phenotype in vitro and in vivo and that autophagy could negatively regulate the canonical pathway of pyroptosis in NPC cells." (PMID 35198448, 2022).
nonalcoholic steatohepatitis (9 papers, 2013 to 2025). "In a phase-2 trial on patients with non-alcoholic steatohepatitis, inhibition of caspase-1, − 8 and − 9 using the GS-9450 compound significantly improved liver function." (PMID 29973136, 2018). "It has been reported that arsenic trioxide (As2O3) resulted in the nonalcoholic fatty liver disease/nonalcoholic steatohepatitis by inducing the classic pyroptosis pathway in HepG2 cells, accompanied by up-regulating the protein expressions of Caspase-1 and IL-1β." (PMID 34439523, 2021). "Previous studies have shown that CPT can reduce the activation of caspase-1 activity and the secretion of IL-1β in mouse models of NLRP3 inflammasome-mediated diseases such as endotoxemia syndrome and nonalcoholic steatohepatitis (NASH)." (PMID 41154678, 2025). "Among them, S1PR1 controls the expression of IL-1β in response to Newcastle disease virus by modulating the NLRP3/caspase-1 inflammasome pathway and enhances inflammation and fibrosis in the kidney, while S1PR4 promotes nonalcoholic steatohepatitis by activating NLRP3 inflammasomes." (PMID 38003456, 2023). "Experimental studies showed that NASH (nonalcoholic steatohepatitis) induced by a high-fat diet is characterized by higher TLR4 expression and NLRP3 inflammasome activation, while the Gal-3 inhibitor reduced liver inflammation and TLR4, NLRP3, and caspase-1 expression levels." (PMID 39125698, 2024).
osteosarcoma (9 papers, 2017 to 2023). A usually aggressive malignant bone-forming mesenchymal neoplasm, predominantly affecting adolescents and young adults. "Among them, MLLT3, ATM/ATR, DDX10, CASP1 and BRD4 have been extensively studied and shown to be associated with pathogenesis or clinical outcomes in osteosarcoma." (PMID 37894336, 2023). "Based on in vitro and in vivo findings, it was reported that expression of caspase-1 and its downstream target Interleukin-1β (IL-1β) was higher in osteosarcoma cells as compared to normal cells." (PMID 36144625, 2022). "In vitro and in vivo administration of BBR to osteosarcoma cells reduces the expression of caspase-1 and Interleukin-1 (IL-1) in tumor cells and inhibits tumor cell development." (PMID 34885950, 2021). "In summary, our study demonstrates that the functional crosstalk between circ-0016347 and miR-214, as well as the down-stream target caspase-1, are critically involved in the proliferation, invasion and metastasis of osteosarcoma cells." (PMID 28424426, 2017). "A large body of evidence has documented that caspase-1 is important for the formation of the tumor microenvironment,contributing to the cell proliferation and invasion of osteosarcoma." (PMID 28424426, 2017). "Taken together, these results illustrated that circ-0016347 probably contributes to the proliferation and invasion of osteosarcoma by allowing an increased expression of caspase-1 with oncogenic potential." (PMID 28424426, 2017). "Circ-0016347 acts as a miRNA sponge to directly inhibit the activity and function of miR-214 and then subsequently increases the expression of the down-stream target caspase-1 in osteosarcoma cells." (PMID 28424426, 2017). "Circular RNA hsa-circ-0016347 promotes proliferation, invasion and metastasis of osteosarcoma cells through acting as a positive regulator in osteosarcoma cells proliferation and invasion, and miR-214 regulates the expression of caspase-1." (PMID 29383123, 2017). "Collectively, these data illustrate that circ-0016347 negatively correlates with miR-214 and indirectly influences the expression of caspase-1 in the osteosarcoma cells." (PMID 28424426, 2017). "Therefore, we attempted to analyze the relationship between circ-0016347 and caspase-1 in osteosarcoma." (PMID 28424426, 2017). "Therefore, revealing the involvement of circ-0016347/miR-214/caspase-1 in the inflammation-related mechanisms in the progression of osteosarcoma is vitally important for the effective treatment of osteosarcoma." (PMID 28424426, 2017). "Consistent with our hypothesis, the expression levels of caspase-1 were notably increased in the high circ-0016347 osteosarcoma tissue group compared to the levels in the low circ-0016347 group." (PMID 28424426, 2017). "Interestingly, in our previous study, we found that caspase-1 was significantly elevated in osteosarcoma patients." (PMID 28424426, 2017). "Therefore, NLRP3/Caspase-1/GSDMD pathway may be involved in NLRP3-induced carcinogenesis of osteosarcoma." (PMID 34393801, 2021). "Furthermore, a reduced expression of caspase-1 and IL-1β via the administration of berberine could significantly suppress the cell viability in osteosarcoma." (PMID 34393801, 2021). "Suppression of NLRP3 protein by its targeted inhibitor CY-09 or knockdown of the NLRP3 gene could inhibit the cell proliferation, migration, invasion, promote apoptosis and G0/G1 cell cycle arrest in osteosarcoma cells in vitro via NLRP3/Caspase-1/GSDMD pathway." (PMID 34393801, 2021). "By the Lasso Cox regression analysis, 6 key PRGs were screened for constructing the optimal model, namely CHMP4C, GZMA, BAK1, CASP1, CASP6, and GSDMA, and a six PRGs signature was successfully constructed for osteosarcoma." (PMID 36244998, 2022). "The present results of the western blot revealed that the NLRP3 as well as caspase-1, GSDMD, IL-1β, and IL-18 proteins decreased after NLRP3 blockage in osteosarcoma." (PMID 34393801, 2021).
osteosarcoma (continued). "Our previous experiments have found that the expression of caspase-1 was higher in osteosarcoma tissues than that in the matched adjacent non-tumor tissues." (PMID 28424426, 2017). "However, to the best of our knowledge, the role of caspase-1 and its upstream regulators in osteosarcoma have not been clarified." (PMID 28424426, 2017).
retinal degeneration (9 papers, 2017 to 2025). Degeneration of the retina. "Caspase-1 is activated after assembly of the inflammasome complex and is involved in inflammasome mediated cell death in retinal degenerations." (PMID 40003961, 2025). "Further research into the role of both Gasdermin D and pyroptosis in the progression of retinal degenerations however, is necessary, in addition to exploring the therapeutic targeting of CASP-1." (PMID 32041990, 2020). "Our study highlights CASP-1 as an important mechanistic target for reducing inflammasome mediated cell death in retinal degenerations and for therapeutic intervention." (PMID 32041990, 2020). "To elucidate the contribution of the inflammasome in the progression of retinal degenerations, we used Casp1/11−/− mice to investigate the role of the inflammasome Caspases, CASP-1 and CASP-11 in the retina." (PMID 32041990, 2020). "In contrast, a more recent study showed that Caspase-1/11 ablation has a protective role in retinal degeneration." (PMID 33246504, 2020). "Results from this study suggest that CASP-1-dependent inflammasomes are responsible for the propagation of inflammation and cell death in photo-oxidative damage-induced retinal degenerations." (PMID 32041990, 2020). "We suggest that in retinal degenerations, CASP-1 propagates retinal inflammation and photoreceptor cell death via the cleavage and activation of pro-inflammatory cytokine IL-1β as well as possibly through its role in Gasdermin D pyroptotic pore formation." (PMID 32041990, 2020). "NLRP3 is the best characterised CASP-1-dependent inflammasome sensor protein, and although widely studied, its role in the progression of retinal degenerations such as AMD has yet to be fully elucidated." (PMID 32041990, 2020). "Little has been reported on ASC in the literature, specifically in relation to retinal degenerations, however, what is clear is that from gene expression studies, Asc gene up-regulation can be mirrored to that of Casp-1 and Il-1β, along with cell death." (PMID 32041990, 2020). "Caspase 1 (Casp1), a gene involved in retinal degeneration, was upregulated in coneΔVhl mice at 8 weeks and peaked at 12 weeks of age." (PMID 29514656, 2018). "In addition to NLRP3, the role of alternative CASP-1-dependent inflammasome components in retinal degenerations was also investigated." (PMID 32041990, 2020). "Results from this study demonstrate an important function of CASP-1 inflammasomes in mediating retinal degenerations, with Casp1/11−/− mice having significantly better-preserved retinal function, increased photoreceptor survivability, and decreased inflammation compared to controls." (PMID 32041990, 2020). "Therapeutic targeting of CASP-1 may offer a more promising avenue to delay the progression of retinal degenerations." (PMID 32041990, 2020). "Despite the evidence pointing toward an important function of IL-1 in photoreceptor death, a previous study has shown that Ilr1 and Casp1 deletion was not protective in a light-model of retinal degeneration." (PMID 33246504, 2020). "To identify whether inflammasome components in addition to CASP-1 might be responsible for the progression of retinal degenerations, we tested mice lacking NLRC4, AIM2 or ASC in our model of retinal degeneration." (PMID 32041990, 2020).
chlamydial infection (8 papers, 2012 to 2025). "It is intriguing that cytoplasmic K+ efflux is required during productive chlamydial infection to activate caspase-1." (PMID 33467438, 2021). "In cervical epithelial cells infected by C. trachomatis, caspase-1activation contributes to the development of chlamydial infection, but caspase-1-dependent caspase-7 activation restricts Legionella pneumophila replication in macrophages and in mice." (PMID 22558425, 2012). "in 2017 showed that both LPS/ATP and murine chlamydial infection of mouse bone marrow-derived macrophages (BMDM) could lead to caspase-1 cleavage and IL-1β released." (PMID 38333214, 2024). "In our chlamydial infection model based on primary human synovial cells, we demonstrated that C. trachomatis infection might induce the canonical inflammasome pathway promoting caspase-1 gene expression." (PMID 34947890, 2021). "This transient activation of ROS during chlamydial infection may initiate signaling cascades like the activation of caspase-1 and Hif-1alpha, which are beneficial for the bacterial development." (PMID 23077614, 2012). "However, unlike LPS/ATP, the inflammatory molecular switch RIP3 was not involved in the activation of NLRP3 inflammatory vesicles in murine Chlamydia-stimulated BMDM, suggesting that chlamydial infection leads to caspase-1 cleavage and IL-1β release by a different mechanism than LPS/ATP." (PMID 38333214, 2024). "Chlamydial infections such as C. pneumoniae developed immune events through the INFα/β, TNF-α, MAPK/ERK, NLRP3/ASC/caspase- 1, JAK/STAT, PI3 K/Akt signaling pathways." (PMID 40275124, 2025). "CtD infected NLRP3−/−, Casp1/11−/−, IL-1β−/−IL-18−/−, and IL-1R−/− mice all exhibited significantly greater infectious loads at day 3 and 7 pi showing NLRP3/Caspase1 inflammasome signaling pathway is critical for controlling early chlamydial infection." (PMID 34526512, 2021). "Indeed, although caspase 1-deficient mice display much reduced genital tract inflammatory damage following chlamydial infection, the mice experience similar courses of infection, indicating that caspase 1 does not have a direct role in the establishment and progression of the infection." (PMID 28281536, 2017).
chronic kidney disease (8 papers, 2015 to 2026). Impairment of the renal function secondary to chronic kidney damage persisting for three or more months. "Future studies will be required to examine the effects of caspase-1 inhibition on chronic kidney diseases." (PMID 30670928, 2018). "The activation of the ROS/NLRP3/caspase-1 signaling pathway induced by oxidative stress can also lead to endothelial dysfunction and pyroptosis in chronic kidney disease (CKD)." (PMID 36304156, 2022).
Crohn disease (8 papers, 2021 to 2025). A gastrointestinal disorder characterized by chronic inflammation involving all layers of the intestinal wall, noncaseating granulomas affecting the intestinal wall and regional lymph nodes, and transmural fibrosis. "Single-cell analysis suggested CASP1 helps reshape the immune microenvironment in Crohn’s disease." (PMID 41595424, 2025). "Furthermore, IL-18 is a critical pro-inflammatory cytokine secreted by IECs of colons from Crohn’s disease patients, involved in an inflammatory caspase-1-dependent manner." (PMID 36120344, 2022). "To date, caspase-1 is the most widely studied cysteine protease that regulates the pyroptosis pathway via inflammasome NLRP3 activation, which has been associated with susceptibility to Crohn’s disease." (PMID 36120344, 2022). "Involved in the treatment of the following caspase-1-related diseases:IBD;Crohn’s disease;RA." (PMID 40431305, 2025).
familial Mediterranean fever (8 papers, 2009 to 2024). Familial Mediterranean fever (FMF) is an autoinflammatory disorder characterized by recurrent short episodes of fever and serositis resulting in pain in the abdomen, chest, joints and muscles. "In the familial Mediterranean fever (FMF) pathologic pyrin variants can increase caspase-1 activation." (PMID 33562758, 2021). "The familial Mediterranean fever (FMF) gene (MEFV) encodes pyrin, a major regulator of the inflammasome platform controlling caspase-1 activation and IL-1β processing." (PMID 19784369, 2009). "In familial Mediterranean fever, pyrin has been shown to function also as an autophagy receptor that targets the inflammasome components NLRP3, NLRP1, and caspase-1 for degradation." (PMID 38593810, 2024). "Active caspase 1 is crucial for the proteolytic activation of Interleukin (IL)-1β, which acts as the major cytokine in multisystem autoinflammatory disorders such as Familial Mediterranean Fever (FMF)." (PMID 36009585, 2022). "A number of mutations in human Pyrin have been reported and associated with the most common human autoinflammatory disease, Familial Mediterranean Fever (FMF), where the pathology is believed to be initiated by hyperactivation of Pyrin-Asc-caspase-1 inflammasomes." (PMID 27911947, 2016).
glomerulonephritis (8 papers, 2011 to 2025). A renal disorder characterized by damage in the glomeruli. "demonstrates that in a model of anti-glomerular basement membrane crescentic glomerulonephritis, endogenous glomerular cells cannot induce glomerulonephritis through the NLRP3–ASC–caspase-1 axis." (PMID 41357229, 2025). "Here, we also observed a statistically significant increase in IL-1β serum level of glomerulonephritis-HD patients which can further support the activation of the NLRP3-ASC-caspase-1 axis in these patients." (PMID 34904012, 2021). "To determine the role of NLRP3, ASC, and caspase-1 in glomerulonephritis, we induced heterologous anti-GBM nephritis in mice with targeted deletions of Nlrp3, Asc, and caspase-1." (PMID 22046355, 2011). "Moreover, recent findings in an ANCA-induced glomerulonephritis model using mice deficient in either of the NADPH oxidase subunits, gp91phox or p47phox, suggested that ROS limit ANCA-induced inflammation by downregulating caspase 1 and hence keep the inflammasome in check." (PMID 27102815, 2016). "Together, genes that are related to the NLRP3-ASC-caspase-1 axis are induced during progressive glomerulonephritis but only in the tubulointerstitium and not in the glomerular compartment of the kidney." (PMID 22046355, 2011).
hyperhomocysteinemia (8 papers, 2016 to 2023). A serious metabolic condition caused by mutations in the MTHFR gene, medications, or nutritional deficiency. "We found that hyperhomocysteinemia resulted in larger atherosclerotic plaques and more secretion of inflammatory cytokines, while these effects were attenuated in Caspase-1 knockdown mice." (PMID 37308812, 2023). "Previous study on hyperhomocysteinemia kidney damage revealed that NLRP3, ASC, caspase-1 all expressed in mice sertoli cell, and homocysteine activated the NLRP3 inflammasome, followed by cytoskeleton rearrangement." (PMID 27721494, 2016). "In hyperhomocysteinemia, activation of the NLRP3 inflammasome has been shown to occur in the contexts of podocyte damage and glomerular sclerosis, and reductions of NADPH oxidase levels, knockdown of ASC, or inhibition of caspase-1 may have a protective effect." (PMID 34267672, 2021).